FGFBP1 (fibroblast growth factor binding protein 1)
Diseases named in the same sentence as FGFBP1 in open-access papers (continued):
Sharing a sentence is not in itself a finding about the gene and the disease.
lymphoma (1 paper, 2024). A malignant (clonal) proliferation of B- lymphocytes or T- lymphocytes which involves the lymph nodes, bone marrow and/or extranodal sites. "These outcomes highlight its selective inhibitory effects on lymphoma cell growth by downregulating FGFBP1 expression through intrinsic apoptosis, causing mitochondrial and DNA damage, ultimately leading to the inhibition of lymphoma progression." (PMID 39005939, 2024). "The overexpression of FGFBP1 raises the pharmacological sensitivity of B4, supplementing its specific action on lymphoma cells." (PMID 39005939, 2024). "This study presents such a novel mechanism by which B4 inhibits the development of lymphoma by targeting FGFBP1-mediated signaling, leading to caspase-dependent intrinsic apoptosis both in vitro and in vivo." (PMID 39005939, 2024). "In conclusion, the research findings indicate that the B4 treatment in lymphoma cells results in a durable binding to FGFBP1." (PMID 39005939, 2024). "However, the therapeutic potential of obstructing FGFBP1 by small molecules or bioactive phytochemicals is a novel strategy in lymphoma therapeutics." (PMID 39005939, 2024). "We found that B4 can trigger apoptosis by FGFBP1 inhibition in lymphoma cells." (PMID 39005939, 2024). "B4 also represses the growth of patient-derived primary lymphoma cells through FGFBP1 inhibition." (PMID 39005939, 2024). "Therefore, this study emphasizes the potential significance of FGFBP1 as an originator of caspase-dependent apoptosis in lymphoma cells." (PMID 39005939, 2024). "Thus, in this study, a flavonoid B4, isolated from Cajanus cajan, has been investigated for its effects of B4 on lymphoma, specifically as an FGFBP1 inhibitor." (PMID 39005939, 2024). "Therefore, the objective of this study is to explore the potential anti-lymphoma effect of B4, specifically focusing on its ability to inhibit FGFBP1 and trigger caspase-dependent apoptosis." (PMID 39005939, 2024). "These suggest B4 may be a novel FGFBP1 inhibitor for the lymphoma treatment." (PMID 39005939, 2024). "Therefore, inhibiting FGFBP1 could significantly slow down lymphoma progression through triggering apoptosis." (PMID 39005939, 2024).
melanoma (1 paper, 2021). A malignant, usually aggressive tumor composed of atypical, neoplastic melanocytes. "FGFBP1 was identified as a prometastasis gene in HCC, whereas S100 family genes' expressions, particularly S100A7, were high in primary melanoma samples but low in metastatic melanoma." (PMID 35003328, 2021).
muscular atrophy (1 paper, 2017). The loss of muscle tissue due to inactivity or disease. "However, after one year from symptoms onset, FGFBP1 and MIR206 levels decrease, which may cause the muscle to be less prone to react to denervation and muscular atrophy." (PMID 28842714, 2017).
myopia (1 paper, 2009). "In such a case the neighboring gene fibroblast growth factor binding protein-1 (FGFBP1; OMIM 607737), located approximately 30 kb from PROM1, is a potential candidate gene for the observed myopia." (PMID 19718270, 2009).
prostate tumor (1 paper, 2009). "FGFBP1 is secreted from AR+ PC3 cells in response to androgen, and is highly expressed in some human prostate tumor cells and the proliferation of these cells was dependent on these high expression levels." (PMID 20027305, 2009).
vascular tumors (1 paper, 2014). "More specifically, we have found that a secreted FGF-binding protein (FGFBP1 or BP1) is produced by KS spindle cells, and by mononuclear cells infiltrating these vascular tumors." (PMID 25429350, 2014).
tumor (31 papers, 2009 to 2026). "We next investigated the underlying mechanism by which the tumor cell–derived FGFBP1-triggered activation of the FGF2/FGFR1 axis induced FAPα expression in HSCs." (PMID 35951441, 2022). "The high expression of FGFBP1 was significantly associated with the degree of tumor differentiation (p = 0.012), age (p = 0.045), and lymph node metastasis (p = 0.032) of ESCC patients." (PMID 33381388, 2020). "The expression of FGFBP1 with ESCC was associated with tumor differentiation degree, age, and lymph node metastasis." (PMID 33381388, 2020). "However, only overexpression of FGFBP1 gene showed association with advanced tumor grade." (PMID 34061869, 2021). "RNA sequencing revealed that HMGA1 regulated transcriptional networks involved in tumor progression and angiogenesis, including the FGFBP1 gene." (PMID 41943828, 2026). "Our findings highlight a novel paradigm where HMGA1 and FGFBP1 drive tumor progression and angiogenesis, presenting them as potential therapeutic targets for HNSCC." (PMID 41943828, 2026). "Here, we identify an epigenetic mechanism whereby HMGA1 promotes tumor progression and angiogenesis via upregulation of fibroblast growth factor-binding protein 1 (FGFBP1)." (PMID 41943828, 2026). "The expression level of HBp17/FGFBP-1 in tumor cells demonstrated a correlation with cell proliferation, and HBp17/FGFBP-1 can be considered a therapeutic target molecule." (PMID 38713345, 2024). "Bevacizumab-resistant tumor cell-derived FGFBP1 induced fibroblast activation protein α expression by enhancing the paracrine FGF2/FGFR1/ERK1/-2/EGR1 signaling pathway in hepatic stellate cells." (PMID 39668826, 2024). "Knockout (KO) of the HBp17/FGFBP-1 by genome editing significantly suppressed tumor growth, cell motility, and tumorigenicity compared with control cells." (PMID 38713345, 2024). "Mechanistically, KLF5 exerts its tumor promotion effect by up-regulating fibroblast growth factor binding protein 1 (FGF-BP1) and snail family transcriptional repressor 2 (SNAIL2)." (PMID 38087142, 2023). "Mechanistically, bevacizumab treatment induced hypoxia to upregulate the expression of fibroblast growth factor–binding protein 1 (FGFBP1) in tumor cells." (PMID 35951441, 2022). "FGFBP1 was higher than the A3 cell line, indicating that the gene is at a higher level in the tumor and is influenced by estrogens, being a good marker for breast carcinogenesis." (PMID 36430763, 2022). "Taken together, our results suggest that tumor cell–derived FGFBP1 induces FAPα expression in HSCs and promotes vessel co-option." (PMID 35951441, 2022). "Gain- or loss-of-function experiments revealed that the bevacizumab-resistant tumor cell–derived FGFBP1 induced FAPα expression by enhancing the paracrine FGF2/FGFR1/ERK1/-2/EGR1 signaling pathway in HSCs." (PMID 35951441, 2022). "The transcription factor can bind with PTN (Pleiotrophin) or FGFBP1 (Fibroblast growth factor-binding protein 1) promoter, which are crucial for tumor growth and then inactivates them." (PMID 31121863, 2019). "Several studies have established FGFBP1 as an oncogenic factor within the tumor microenvironment by virtue of its activation of proliferative FGFR signaling pathways, a mechanism consistent with the well-documented pro-proliferative effects observed in various cancer models." (PMID 40427333, 2025). "HBp17/FGFBP-1 inhibition suppressed the growth of tumor xenografts and angiogenesis in mice." (PMID 38713345, 2024). "The expression level of FGFBP1 was higher in tumor tissues compared with normal tissues." (PMID 37575248, 2023). "The AUC value for FGFBP1 to discriminate between tumor and normal was 0.895." (PMID 37575248, 2023). "Tumor cell–derived FGFBP1 induces FAPα expression in HSCs via the FGF2/FGFR1/ERK1/-2/EGR1 axis." (PMID 35951441, 2022). "Another possibility might be the important role of FGFBP1 in tumor angiogenesis and cancer progression." (PMID 36119059, 2022).
tumor (continued). "However, coculture with LSECs had negligible effects on the expression of FGFBP1 in tumor cells and the tumor cell–primed expression of FAPα in HSCs." (PMID 35951441, 2022). "Tumor cell–derived FGFBP1 induces FAPα expression in HSCs to promote vessel co-option." (PMID 35951441, 2022). "Here, we demonstrated that bevacizumab treatment induced tumor hypoxia to upregulate the expression of FGFBP1 in tumor cells, which activated the FGF2/FGFR1 signaling pathway to promote HSCs’ transformation into multiple phenotypes, including an “immunogenic” phenotype." (PMID 35951441, 2022). "However, as FGFR1 is also expressed on tumor cells, we here cannot exclude the contribution of the activation of FGFBP1/FGF2/FGFR1 signaling in tumor cells for vessel co-option." (PMID 35951441, 2022). "Our previous studies demonstrated that KLF5 promoted cell survival, proliferation and tumor growth partially through direct up-regulation of fibroblast growth factor binding protein 1(FGF-BP) and microsomal prostaglandin E2 synthase 1 (mPGES1) gene transcription." (PMID 26079537, 2015). "This study also showed that HBp17/FGFBP-1 expression is affected by calcitriol via the NF-κB pathway (IκBα up-regulation), thus suggesting this molecule may have a potential role as a target for anti-tumour therapy by calcitriol." (PMID 37299554, 2023). "In addition, FGF2 and p-FGFR1 were highly expressed in FAPα+ HSCs in the co-opted sinusoidal blood vessels in bevacizumab-resistant HCT116 and HT-29 CRCLM xenografts, indicating that tumor cell–derived FGFBP1 might induce FAPα expression in HSCs by activating the FGF2/FGFR1 signaling pathway." (PMID 35951441, 2022). "Data on the FGF2, FGFBP1, TGFA, TGFBR3, and IGF1R expression levels were analyzed using TIMER 2.0 that matched TCGA tumor tissue with normal tissue." (PMID 36430763, 2022). "We found that fibroblast growth factor-binding protein (FGFBP1) was the carrier molecule of FGF2, which was first found in tumor cell lines." (PMID 33381388, 2020). "In previous studies we have found that a Fibroblast Growth Factor Binding Protein (FGFBP1 or BP1), which was first identified in a tumor cell line, is a carrier molecule for FGF-2." (PMID 25429350, 2014). "In summary, we have shown that a FGF binding protein (FGFBP1) which is known to positively modulate the angiogenic and growth promoting activity of FGF’s in tumor cells, is expressed in keratinocytes, infiltrating mononuclear cells, and KS spindle cells." (PMID 25429350, 2014). "Blocking HMGA1, FGFBP1, or FGFR1 also reduced stromal formation and increased tumor necrosis." (PMID 41943828, 2026). "As described, FGFBP1, STC1, and NPNT proteins have tumor‐promoting effect thus, downregulation of these proteins could have contributed to the synergistic effect in our study." (PMID 38217262, 2024). "As key cells involved in pro-tumour angiogenesis, HSCs have been demonstrated to upregulate fibroblast activation protein alpha (FAPα) and increase CXCL5 secretion, as regulated by cancer cell-secreted fibroblast growth factor-binding protein 1 (FGFBP1)." (PMID 37480104, 2023). "Additionally, we reported that 1α,25(OH)2D3 or eldecalcitol (ED-71), which is an analog of 1α,25(OH)2D3, suppresses HBp17/FGFBP-1 expression and tumor growth in vitro and in vivo by inhibiting the nuclear factor kappa-light-chain-enhancer of activated B cells signaling pathway." (PMID 38713345, 2024). "The expression of FGFBP1 with ESCC cases of tumor differentiation (p = 0.012), age (p = 0.045), and lymph node metastasis (p = 0.032) has more obvious relationship, rather than gender, tumor size, tumor location, pathological stage, and vascular invasion of clinical pathology features." (PMID 33381388, 2020).
cancer (30 papers, 2013 to 2025). A tumor composed of atypical neoplastic, often pleomorphic cells that invade other tissues. "FGFBP1 is a soluble intracellular protein that progresses cancer cell proliferation and is upregulated in several cancers." (PMID 39005939, 2024). "Compared to its low expression in normal tissues, FGFBP1 expression level is higher in various cancers." (PMID 37575248, 2023). "Consistently, we found that several downregulated genes associated with cancer cells metabolism (Pfkfb3, Fgfbp1, Gnas, Pfkfb4, Ctnnb1, and Tsta3) in the colon of EgPSC-infected mice, indicating that intraperitoneally EgPSC infection may elicit protective effect in cancer development." (PMID 36713407, 2022). "The results indicate that calcitriol may be used as a potential factor to restrict the activity of HBp17/FGFBP-1 in cancer cells (UE cells) treated with 40 nM 1α,25(OH)2D3." (PMID 37299554, 2023). "We observed significantly higher levels of FGFBP1 in benign lesions compared to cancer." (PMID 30019538, 2018). "The high expression of ARG2, FGFBP1 and FOXM1, are associated with several cancers." (PMID 24481205, 2013). "In cancer biology, FGFBP1 may stimulate angiogenesis, PD‐L1 expression, and immune inhibition." (PMID 38217262, 2024). "Therefore, the inhibition of FGF2, FGFR3, and FGFBP1 may enhance the efficacy of chemotherapy, which is hopeful to make it an irreplaceable sensitizing target for cancer treatment." (PMID 33381388, 2020). "However, abnormal expression of FGFBP1 often indicates the occurrence of carcinomas." (PMID 31058187, 2019). "FGFBP1 has been reported to bind FGF1 and FGF2 and enhance biological activities in carcinoma cells." (PMID 40685360, 2025). "We revealed a novel anticancer mechanism that involves HBp17/FGFBP-1 function regulation by exosomal miR-6887-5p in SCC/OSCC cells, which has potential as a target for miRNA-based cancer therapy." (PMID 38713345, 2024). "It activates the expression of NANOG and FGFBP1 in TNBC, which are required for the maintenance of the cancer stem cell (CSC) population." (PMID 38468288, 2024). "FGFBP1 amplifies FGF signaling pathways thereby promoting angiogenesis, a crucial course in cancer advancement." (PMID 39005939, 2024). "Upregulation was observed in many genes, including CAV2, FGFBP1, KRT19, MST1R, OCLN, and RGS2, which play important roles in the negative regulation of EMT and metastasis phenotypes in many cancers." (PMID 37298519, 2023). "FGFBP1 enhances FGF signaling, including angiogenesis during cancer progression, and is upregulated in various cancers." (PMID 36430763, 2022). "Elevated FGFBP1 facilitates cancer growth and metastasis, which was demonstrated to act as an angiogenic switch molecule in cancer by enhancing FGF signaling including angiogenesis during cancer progression." (PMID 36119059, 2022). "In addition, the levels of FGFBP1, DCN, FUR, and CXCL9 differed significantly between the benign and cancer groups by univariate analysis (ANOVA)." (PMID 30019538, 2018). "In addition, HBp17/FGFBP-1 binds reversibly to FGF-1 and FGF-2 in vitro, so it may be related to the secretion and activation of FGFs and may control cancer cell growth." (PMID 34072393, 2021).
FGFBP1 also shares sentences with these, for which no sentence is quoted: hepatocellular carcinoma (3 papers); acute kidney injury (1); adenocarcinoma (1); adrenal carcinoma (1); Anxiety (1); benign salivary gland tumor (1); breast (1); cerebrovascular disease (1); chronic asthma (1); co-infection (1); colorectal adenocarcinoma (1); colorectal cancer (1); cutaneous squamous cell carcinoma (1); dysplasia (1); esophageal carcinoma (1); hemolytic-uremic syndrome (1); infection (1); ischemia (1); metastatic melanoma (1); neuromuscular disease (1); osteoarthritis (1); ovarian carcinoma (1); psoriasis (1); squamous cell carcinoma of the skin (1); triple-negative breast carcinoma (1).